ALPK3 (alpha kinase 3)
Description:
Involved in cardiomyocyte differentiation.
Synonyms: KIAA1330; MAK; Midori; CMH27
Tractability: No criterion of Open Targets' tractability assessment is met for any kind of drug.
Target class: Enzyme; Transferase
Gene: Protein-coding gene on chromosome 15 (84,817,176 to 84,873,479, forward strand). Ensembl gene ENSG00000136383.
Subcellular location: Nucleus
Subcellular location (Human Protein Atlas): Nucleoplasm
Gene Ontology:
Molecular function: protein serine kinase activity; ATP binding; protein serine/threonine kinase activity
Biological process: cardiac muscle cell development; heart development; cardiac muscle cell differentiation
Cellular component: nucleus
Genetic constraint (gnomAD): Loss-of-function variants: 105 observed, 141.23 expected, observed/expected ratio (o/e) 0.74, 90% interval 0.63 to 0.87. The upper end of that interval is the gene's LOEUF score, 0.87, which puts it in group 3 of 6, group 1 being the genes least tolerant of losing a copy. Missense variants: 2,250 observed, 2,223.8 expected, observed/expected ratio (o/e) 1.01, 90% interval 0.98 to 1.05. Synonymous variants: 937 observed, 906.83 expected, observed/expected ratio (o/e) 1.03, 90% interval 0.98 to 1.09.
Gene-disease validity (ClinGen):
ClinGen rates the evidence that ALPK3 causes each of these diseases.
hypertrophic cardiomyopathy (autosomal recessive): Definitive. A condition in which the myocardium is hypertrophied without an obvious cause.
hypertrophic cardiomyopathy (autosomal dominant): Strong.
Homologues: Orthologues: chimpanzee ALPK3 (99% identical), macaque ZNF592 (92% identical), pig ALPK3 (78% identical), dog ALPK3 (76% identical), rat Alpk3 (73% identical), mouse Alpk3 (72% identical), rabbit ALPK3 (68% identical), guinea pig ALPK3 (66% identical), zebrafish alpk3b (26% identical), tropical clawed frog alpk3 (19% identical), Drosophila melanogaster bt (12% identical), Caenorhabditis elegans unc-22 (12% identical), and 2 more. Paralogues in human: HMCN1 (16% identical), OBSCN (15% identical), MYPN (13% identical), SPEG (12% identical), IGFN1 (10% identical), PALLD (9% identical), CCDC141 (6% identical), MYOT (5% identical), SPEGNB (2% identical).
Diseases named in the same sentence as ALPK3 in open-access papers:
ALPK3 is named in the same sentence as 54 diseases in open-access papers, as found by Europe PMC text mining. Sharing a sentence is not in itself a finding about the gene and the disease. The quoted sentences say what the papers report.
cardiomyopathy (31 papers, 2017 to 2025). A disease of the heart muscle or myocardium proper. "ALPK3 was identified in all analyses, and although primarily implicated cardiomyopathy, this gene has been identified as a plasticity candidate in a gene expression analysis of temperature responses in stickleback." (PMID 39415606, 2025). "This loss of M-band MYOM1 was also observed in CMs harboring HCM-associated ALPK3 variants and was highly disorganized in a mouse model of ALPK3 cardiomyopathy." (PMID 39196058, 2023). "Pathogenic variants in alpha kinase 3 (ALPK3) cause cardiomyopathy and musculoskeletal disease, but little is known about this atypical kinase." (PMID 39196058, 2023). "We conclude that ALPK3 cardiomyopathy induces ventricular dilatation caused by insufficient myomesin-mediated force buffering and hypertrophy by impairment of sarcomere proteostasis." (PMID 36321451, 2022). "ALPK3 loss-of-function variants cause cardiomyopathy with distinctive clinical manifestations in both children and adults, but the molecular functions of ALPK3 remain poorly understood." (PMID 36321451, 2022). "We reidentified all five loci harboring Mendelian cardiomyopathy-linked genes found in prior common variant analyses of DCM (ALPK3, BAG3, FLNC, PLEKHM2, and TTN)." (PMID 32382064, 2020). "We reported two new cases of cardiomyopathies with skeletomuscular features associated with the ALPK3 gene." (PMID 33076350, 2020). "This further includes the variability of the skeletal and muscle system involvement in ALPK3-associated cardiomyopathy." (PMID 33076350, 2020). "In conclusion, the two patients in our study further showed the variability of symptoms and onset of disease that is seen in cases of cardiomyopathy caused by variations in the ALPK3 gene." (PMID 33076350, 2020). "In Patient 2, target sequencing, using a panel of 173 cardiomyopathy-associated genes, combined with filtering and sorting of the variants, revealed a homozygous nonsynonymous single-nucleotide variant in exon 10 of ALPK3 (NM_020778): c.G4897A: p.G1633R." (PMID 33076350, 2020). "Together with other reported cases we further stressed the importance of skeletal and neuromuscular system examination in patients with ALPK3-associated cardiomyopathy, especially in view of possible need of cardiac transplantation in the future." (PMID 33076350, 2020). "ALPK3 encodes a nuclear kinase implicated in the differentiation of cardiomyocyte and Alpk3-deficient mice develop cardiomyopathy." (PMID 28296976, 2017). "To date, only two studies have reported homozygous pathogenic variants of ALPK3, with a total of seven affected individuals with cardiomyopathy from four unrelated consanguineous families." (PMID 28630369, 2017). "Here we report a null variant in the autosomal recessively inherited cardiomyopathy gene ALPK3, which was identified in a patient who initially presented with DCM that later progressed to HCM." (PMID 28630369, 2017). "In this study, we report a case of HCM associated with a homozygous ALPK3 missense variant identified at a young age, which may indicate a role of missense variants in the development of autosomal-recessive ALPK3 cardiomyopathy." (PMID 41440877, 2025). "It was first reported in pediatric cardiomyopathy that patients with biallelic truncating genetic variants in ALPK3 (ALPK3tv) displayed a phenotype of dilated cardiomyopathy (DCM) in utero, at birth, or early childhood, and often evolved to an HCM phenotype over time." (PMID 35783621, 2022). "The alpha kinase 3 (ALPK3) gene was only recently described in connection to severe forms of pediatric cardiomyopathy, myopathic and dysmorphic skeletal features, while the mouse model of Alpk3-associated cardiomyopathy was described in 2012." (PMID 33076350, 2020). "Additionally, in a recent study, the first case of symptomatic ALPK3-associated cardiomyopathy presenting in adulthood is reported, leading to cardiac transplantation 10 years after the presentation of symptoms." (PMID 33302605, 2020).
cardiomyopathy (continued). "Therefore, the detailed degree of skeletal and muscle system involvement, as well as intellectual and endocrine status in ALPK3- associated cardiomyopathy cases, need to be further delineated." (PMID 33076350, 2020). "A mutation in the ALPK3 gene in human is associated with cardiomyopathy." (PMID 32143402, 2020). "Two previously reported cases of adult ALPK3-associated cardiomyopathy described by Al Senaidi and co-authors were detected using cascade family screening and presented no clinical symptoms by the third and fourth decades of life, in spite of homozygote status." (PMID 33076350, 2020). "New evidence asserting autosomal dominantly inherited loss of function variants in ALPK3 prompted pre-curation to determine the disease entities to be curated, with a decision to consider this a disease entity distinct from childhood-onset autosomal recessive ALPK3 cardiomyopathy." (PMID 39132495, 2024). "We suspect that the hypertrophy caused by ALPK3 cardiomyopathy in surviving newborns with recessive pathogenic variants and adults with heterozygous pathogenic variants may be related to additional roles of ALPK3 in directly or indirectly regulating sarcomere protein turnover at the M-band." (PMID 36321451, 2022). "Available reports have hitherto shown high variability in the clinical manifestations of ALPK3-related cardiomyopathy, but the data on genotype–phenotype correlation are still scarce due to the limited number of published studies." (PMID 39062799, 2024). "We also present the first example of a splicing functional study for ALPK3 and describe the genotype–phenotype correlations in cardiomyopathy." (PMID 39062799, 2024). "The matter is further complicated when speaking of the extracardiac features of ALPK3-dependent cardiomyopathy." (PMID 39062799, 2024). "We suggest that ALPK3 PTV carriers be considered a risk group for developing HCMP and be monitored for cardiomyopathies." (PMID 39036505, 2024). "Though sometimes ALPK3-related cardiomyopathy is referred to as “Noonan-like”, published observations to date demonstrate that the full spectrum of extracardiac manifestations is much wider than in Noonan-like disorders." (PMID 39062799, 2024). "The first paper linking the ALPK3 gene to cardiomyopathies was published in 2016 and focused on biallelic truncating variants in this gene, considering them to be the cause of severe autosomal recessive (AR) cardiomyopathy with neonatal onset." (PMID 39062799, 2024). "The following publications highlighted some distinct features specific to ALPK3-dependent AR cardiomyopathy, such as an unusual progression of neonatal dilated cardiomyopathy to HCM and various facial and musculoskeletal dysmorphisms." (PMID 39062799, 2024). "Beyond the recognized causal genes for Mendelian cardiomyopathy such as FHOD330 and ALPK3,31,32 a number of prioritised genes merit further discussion." (PMID 36598836, 2023). "ALPK3 is a vital kinase in cell differentiation, and ALPK3 knockout mice demonstrate both hypertrophic and dilated forms of cardiomyopathy." (PMID 36456907, 2022). "Though the ALPK3 gene was less reported in chickens, it has been comprehensively studied in the cardiomyopathy of mammals." (PMID 36456907, 2022). "Homozygous Alpk3-knockout mice had features of both hypertrophic and dilated forms of cardiomyopathy, reproducing the same phenotype previously reported for an Alpk3 mouse model." (PMID 39195995, 2022). "We report the biochemical and molecular functions of ALPK3 and provide insights into the pathogenesis of ALPK3 cardiomyopathy." (PMID 36321451, 2022). "Alpha-protein kinase 3 (ALPK3), located on chromosome 15q25.2, has recently emerged as a possible candidate gene in cardiomyopathy." (PMID 34263907, 2021). "Both ALPK3 and VCL are associated with cardiomyopathy, and CAND2 is associated with atrial fibrillation and also creatine kinase concentrations." (PMID 33961016, 2021).
cardiomyopathy (continued). "We provide further evidence for involvement of ALPK3 in cardiomyopathy, as well as identify a unique progression of DCM to HCM." (PMID 28630369, 2017). "Given the dysregulation of protein quality control networks in cardiac disease, ALPK3 may be a promising therapeutic target to restore heart function in cardiomyopathies." (PMID 39196058, 2023). "Given our results, which demonstrate mislocalization of SQSTM1 in three independent ALPK3 pathogenic variants, and the growing number of ALPK3 variants linked to HCM15,16, our findings point to a central role for disrupted sarcomeric homeostasis in cardiomyopathy." (PMID 39196058, 2023). "Cardiomyocytes missing ALPK3 may have abnormal calcium handling, offering useful insights into the molecular processes driving ALPK3-mediated cardiomyopathy." (PMID 35677823, 2022). "Serial longitudinal echocardiography beginning at postnatal day 0 showed that Alpk3–/– mice had normal cardiac function at birth but manifested a rapidly progressive cardiomyopathy in the first week of life that resulted in premature death (no survivors beyond 14 weeks)." (PMID 36321451, 2022). "Despite its primordial and persistent cardiac expression and clear role in cardiomyopathy pathogenesis, the molecular functions and putative kinase activity of ALPK3 remain unknown." (PMID 36321451, 2022). "In 2016, the ALPK3 gene was discovered to be a rare cause of a recessive pediatric cardiomyopathy, which typically presents with DCM and non-compaction that progress to hypertrophic cardiomyopathy and possibly some syndromic features." (PMID 33534821, 2021). "Collectively, this study suggests that mutations in ALPK3 can cause familiar cardiomyopathy, identifying abnormal Ca2+ handling as a potential feature of cardiomyocytes lacking ALPK3." (PMID 28573431, 2017). "Overall, lead variants at 9 of the 61 GWS loci were located nearest to known cardiomyopathy genes (ACTN2, ALPK3, BAG3, FLNC, PLN, TTN), representing significant enrichment (hypergeometric p = 6.01 × 10−11)." (PMID 36376295, 2022). "Other highly prioritized genes across multiple lines of evidence include Mendelian cardiomyopathy genes (BAG3, ACTN2, ALPK3)." (PMID 36376295, 2022). "This outcome supports the consideration of the Liwen procedure as an effective therapeutic strategy for complex obstructive ALPK3-related HCM, but the 6-month follow-up is a recognized limitation in evaluating long-term outcomes for this potentially progressive cardiomyopathy." (PMID 41437994, 2025). "We report a case of successful genetic investigation of ALPK3-related cardiomyopathy with LVH, left ventricular noncompaction (LVNC), and extensive fibrosis in a large family with diverse dysmorphological features." (PMID 39062799, 2024). "Alpk3−/− mice exhibited nonprogressive cardiomyopathy that had features of both hypertrophic and dilated forms, which is consistent with observations in the patient of our study." (PMID 28630369, 2017). "Whereas mutations in ALPK3 have been associated with non-sarcomeric hypertrophic cardiomyopathy or dilated cardiomyopathy, BAG3 and RBM20 genes have been associated with dilated cardiomyopathy phenotype further highlighting a potential link between MVP and cardiomyopathy." (PMID 36873395, 2023). "The regulatory roles of other enriched genes in cardiomyopathy networks (including SYNE2, APOB, XIRP1, ALPK3, and LRPPRC) are not clear." (PMID 34236536, 2021).
hypertrophic cardiomyopathy (13 papers, 2020 to 2025). "In that study, 21 individuals with ALPK3 heterozygous truncating variants were reported to have late-onset hypertrophic cardiomyopathy, often with frequent apical involvement and the presence of apical aneurysms." (PMID 40428316, 2025). "Hypertrophic cardiomyopathy associated with damaging variants in the ALPK3 gene is a fairly recent discovery, and only a small number of patients have been described thus far." (PMID 33076350, 2020). "Hitherto, 27 patients with hypertrophic cardiomyopathy, caused by 19 different mutations in ALPK3, have been described." (PMID 33076350, 2020). "Alpk3−/− mice show gross cardiac enlargement with mural thickening typically associated with hypertrophic cardiomyopathy." (PMID 33076350, 2020). "Loss of ALPK3 has been associated with contractile dysfunction and dilated cardiomyopathy in both murine and human models, whereas truncating variants are linked to hypertrophic cardiomyopathy." (PMID 41373456, 2025). "Summarization of reported ALPK3 mutations resulting in hypertrophic cardiomyopathy." (PMID 37396576, 2023). "The aim of this study was to determine the frequency of heterozygous truncating ALPK3 variants (ALPK3tv) in patients with hypertrophic cardiomyopathy (HCM) and confirm their pathogenicity using burden testing in independent cohorts and family co-segregation studies." (PMID 34263907, 2021). "While ALPK3 has been extensively studied in hypertrophic cardiomyopathy, its role in cancer remains largely unexplored." (PMID 40269756, 2025). "Genes associated with Mendelian forms of hypertrophic cardiomyopathy (HCM) (MYBPC3, ALPK3 and FHOD3) were also identified at genomic risk loci for DCM, a finding consistent with evidence that these disorders represent opposing extremes of a continuum of ventricular structure and systolic function." (PMID 39572783, 2024).
dilated cardiomyopathy (7 papers, 2021 to 2025). Cardiomyopathy which is characterized by dilation and contractile dysfunction of the left and right ventricles. "When we clustered the results, one PPI cluster for LVEF is dominated by genes previously implicated with dilated cardiomyopathy and heart failure risk (HSPB7, FLNC, ALPK3, CLCNKA), as well as links to the brain via WDR7391–97." (PMID 39670392, 2025).
Ventricular hypertrophy (6 papers, 2021 to 2024). Enlargement of the cardiac ventricular muscle tissue with increase in the width of the wall of the ventricle and loss of elasticity. "ALPK3-null (−/−) mice develop both ventricular hypertrophy and dilation suggesting the underlying pathomechanism of the disease is loss of function of the ALPK3 gene." (PMID 39036505, 2024). "In previous studies, ALPK3 has been identified as a potential factor associated with myocardial cell differentiation, and mice with functional deficiency of ALPK3 exhibit significant ventricular hypertrophy." (PMID 37396576, 2023). "Our test data confirmed reproducible myocardial hypertrophy in Alpk3-null mice, characterized by increased end-diastolic LVAW and LVPW thickness." (PMID 39195995, 2022). "Recent evidence has shown that ALPK3 participates in intercalated disc and sarcomere structural organization and murine knock-out models show ventricular hypertrophy and impaired contractility." (PMID 34263907, 2021).
heart failure (3 papers, 2021 to 2025). Inability of the heart to pump blood at an adequate rate to meet tissue metabolic requirements. "In this study, we show that truncating variants in ALPK3 cause autosomal dominant HCM characterized by a severe cardiac phenotype with extensive myocardial fibrosis and progression to heart failure." (PMID 34263907, 2021).
Danon disease (2 papers, 2024 to 2025). A lysosomal glycogen storage disease characterized by severe cardiomyopathy and variable degrees of muscle weakness, frequently associated with intellectual deficit. "Adults transplanted before 35 years included all patients with Danon disease (P.8–P.10), one patient with a homozygous missense variant in ALPK3 (P.3), and both patients with TTN variants (P.4–P.5)." (PMID 41440877, 2025). "The dilated phenotype subgroup (P.1–P.10) included all patients with Danon disease, the patient with a homozygous ALPK3 variant, carriers of in-frame deletions in TTN and FLNC, a heterozygous TRIM63 missense variant, and carriers of splice-site variants in MYH7 and MYBPC3." (PMID 41440877, 2025).
familial cardiomyopathy (2 papers, 2022 to 2023). An instance of cardiomyopathy that is caused by an inherited modification of the individual's genome. "Mutations in ALPK3 cause familial cardiomyopathy and demonstrate loss of function as the underlying genetic mechanism." (PMID 38036550, 2023). "ALPK3 has been reported to be closely associated with familial cardiomyopathy, but its role in skeletal muscle has not been reported." (PMID 36032309, 2022).
Obesity (2 papers, 2021 to 2022). Accumulation of substantial excess body fat. "ALPK3, HLF, FXN, and SPTAN1 are the only genes that have never been linked to obesity." (PMID 35677823, 2022).
Onset (2 papers, 2023 to 2025). The age group in which disease manifestations appear. "This has been previously demonstrated by the initial discovery of ALPK3 as a cause of rare early-onset recessive CM and later as a more common subtype of dominant adult-onset HCM." (PMID 38666070, 2023).
osteosarcoma (2 papers, 2019 to 2023). A usually aggressive malignant bone-forming mesenchymal neoplasm, predominantly affecting adolescents and young adults. "A combination of eight genes (RAB1,CLEC3B,FCGBP,RNASE3,MDL1,ALOX5AP,VMO1 and ALPK3) were identified as being associated with osteosarcoma metastasis." (PMID 30868060, 2019). "ALPK3 was identified to be associated with the metastasis of osteosarcoma patients." (PMID 37237274, 2023). "On the contrary, patients with metastatic osteosarcoma tended to have a higher expression level of ALPK3 than those with non‐metastatic osteosarcoma." (PMID 30868060, 2019).
breast carcinoma (1 paper, 2020). "In breast cancer (BRCA), overexpression of six dark kinases is associated with decreased overall survival (ALPK3, CSNK1A1L, CSNK2A3, NRK, POMK, and PSKH1)." (PMID 33205077, 2020).